CDK10 (cyclin dependent kinase 10)
Diseases named in the same sentence as CDK10 in open-access papers (continued):
Sharing a sentence is not in itself a finding about the gene and the disease.
hepatocellular carcinoma (4 papers, 2013 to 2021). A malignant tumor that arises from hepatocytes. "Transient overexpression of CDK10 in human hepatocellular carcinoma cell lines also caused an inhibition of cell proliferation, cell migration and anchorage-independent growth, and it increased sensitivity to cisplatin and epidoxorubicin." (PMID 28178678, 2017). "Recent findings seem to indicate that CDK10 might act as a putative tumor suppressor gene and that a reduced CDK10 expression is quite likely linked with the development and progression of hepatocellular carcinoma." (PMID 23840966, 2013). "The CDK10 gene was mapped to chromosome 16 at location q24, a region that shows loss of heterozygosity (LOH) in a number of cancers including hepatocellular carcinomas." (PMID 28178678, 2017). "Immunohistochemical studies of hepatocellular carcinomas showed that decreased CDK10 protein expression levels were significantly correlated with tumor size, alpha-fetoprotein levels, and tumor stage." (PMID 28178678, 2017).
nasopharyngeal carcinoma (4 papers, 2020 to 2025). A carcinoma arising from the nasopharyngeal epithelium. "Specifically, CDK10 has been identified as a candidate tumor suppressor in hepatobiliary cancers, gastric cancer, glioma and nasopharyngeal carcinoma." (PMID 34277407, 2021).
seminoma (4 papers, 2010 to 2024). A radiosensitive malignant germ cell tumor found in the testis (especially undescended), and extragonadal sites (anterior mediastinum and pineal gland). "CDK10 has the potential to be engaged in the process of cellular differentiation and proliferation, consequently making it a potential target for the prognostication of seminomas." (PMID 38507271, 2024). "Another specific protein for seminomas is Cyclin-dependent kinase 10 (CDK10)." (PMID 31354629, 2019). "Both the CDK10 isoforms are expressed in the nuclear matrix of the seminomas, supporting the role of CDK10 in the cell cycle regulation that may induce testicular cancer." (PMID 31354629, 2019).
Al Kaissi syndrome (3 papers, 2020 to 2023). "On the other hand, CDK10 mutations lead to Al Kaissi syndrome, an autosomal recessive developmental disorder characterized by growth retardation, spine malformation, particularly of the cervical spine." (PMID 33805800, 2021). "The significant differences between the STAR and the Al Kaissi syndromes suggest that CDK10 and/or cyclin M exert more functions than those exerted by the CDK10/CycM protein kinase." (PMID 32762766, 2020). "The distinction between the STAR and the Al Kaissi syndromes is not always clear, as it is difficult to group patients under particular syndrome label, because both cyclin M and/or CDK10 exert more functions than those exerted by the protein kinase heterodimer." (PMID 33805800, 2021).
gastric cancer (3 papers, 2020 to 2023). A primary or metastatic malignant neoplasm involving the stomach. "Consistently, these studies found a significant correlation between loss of CDK10 expression and advanced tumor stage, lymph node invasion and distant metastasis, in patients with gastric cancer." (PMID 34277407, 2021). "Moreover, loss of CDK10 was also associated with poor survival, tumor differentiation, and metastasis in gastric cancer." (PMID 36769170, 2023). "Furthermore, these studies also identified loss of CDK10 expression as an unfavorable prognostic marker in gastric cancer." (PMID 34277407, 2021). "Studies have also assessed the effect of CDK10 on cell proliferation and cell motility in gastric cancers." (PMID 34277407, 2021). "Independent studies found decreased expression of CDK10 in gastric cancer compared to normal gastric tissue." (PMID 34277407, 2021). "CDK10 expression is significantly lower in gastric cancer tissues than in normal tissues." (PMID 36769170, 2023). "Overexpression of CDK10 led to inhibition of invasion, migration, and proliferation of gastric cancer cells whereas the knockdown of CDK10 demonstrated the opposite phenotypes, indicating that CDK10 is downregulated in gastric cancer." (PMID 36769170, 2023). "Additionally, in gastric cancer, overexpression of CDK10 decreased cell invasion, while knockdown of CDK10 promoted cell invasion." (PMID 34277407, 2021). "In addition to hepatobiliary cancers, CDK10 has been identified as a candidate tumor suppressor in gastric cancer." (PMID 34277407, 2021). "CDK10 activity and its expression levels in various cancers have been reviewed and it has been shown that this particular CDK behaves as either an oncoprotein or tumor suppressor depending on the tissues; however, in gastric cancer, the levels of CDK10 are lower than in normal tissues." (PMID 36769170, 2023).
colon carcinoma (2 papers, 2017 to 2020). "Survival analysis using selected hub genes, such as AHSA2, CDK10, and CWC22, showed that their expression levels were significantly associated with the survival rate of colon cancer patients, which indicates their possible use as prognostic markers." (PMID 32345988, 2020). "Conversely, CDK10 was found downregulated in retinoic acid-treated retinoblastoma cells and in butyrate-treated colon carcinoma cells, where both treatments trigger cell cycle arrest." (PMID 28178678, 2017). "In conclusion, using a gene expression network analysis, we have identified hub genes, such as AHSA2, CDK10, and CWC22, as being possible prognostic markers, that were not previously known to be associated with colon cancer." (PMID 32345988, 2020).
glioma (2 papers, 2020 to 2021). A benign or malignant brain and spinal cord tumor that arises from glial cells (astrocytes, oligodendrocytes, ependymal cells). "CDK10 was shown to regulate expression of the EMT transcription factor, Snail, and the effects of CDK10 on EMT in glioma were partially reversed by manipulation of Snail expression." (PMID 34277407, 2021). "In glioma, CDK10 was shown to regulate cell motility through inhibition of epithelial to mesenchymal transition (EMT)." (PMID 34277407, 2021).
pancreatic cancer (2 papers, 2022 to 2024). "This suggested that NSUN6 may influence pancreatic cancer proliferation by regulating CDK10 expression involved in mitotic spindle assembly and mitotic nuclear division." (PMID 38476632, 2024). "Low expression of NSUN6, an m5C methyltransferase, was found in pancreatic cancer patients, and may contribute to pancreatic cancer cell proliferation through regulation of CDK10." (PMID 35350378, 2022).
skin cancer (2 papers, 2021). "This study puts forward a set of genes that could be prioritized in upcoming investigations (e.g. CDK10 or SPIRE2) to delve deeper into the role played by the variability in DNAm as a potentially causal risk factor for skin cancer." (PMID 33248005, 2021).
testicular cancer (2 papers, 2010 to 2019). A primary or metastatic malignant neoplasm that affects the testis. "Although this is the first study to examine the role of nuclear structural proteins as potential biomarkers in testicular cancer, additional studies are clearly warranted to further identify the role of CDK10 as a potential tumor marker for testicular cancer." (PMID 20535291, 2010).
vitiligo (2 papers, 2021 to 2024). Generalized well circumscribed patches of leukoderma that are generally distributed over symmetric body locations and is due to autoimmune destruction of melanocytes. "Our findings revealed that a shared genetic variant rs77651727 alters the cg05175606 as well as up-regulates gene expression of CDK10 and further decreases the risk of vitiligo." (PMID 33679896, 2021). "We further performed SMR and HEIDI by combing GWAS with the largest eQTL data from eQTLGen Consortium, which verified CDK10 as a vitiligo-associated gene." (PMID 33679896, 2021). "We also identified 17 vitiligo-associated DNA methylation (DNAm) sites in Chr16, of which cg05175606 was significantly associated with the expression of CDK10 and vitiligo." (PMID 33679896, 2021). "We also found a candidate shared causal variant (rs77651727) across vitiligo, transcript of CDK10, and cg05175606." (PMID 33679896, 2021). "But SMR and HEIDI analysis has identified the transcript of CDK10 and cg05175606 were associated with vitiligo due to the shared variant rs77651727." (PMID 33679896, 2021). "By integrating omics data, we identified two newly putative functional genes (SPATA2L and CDK10) associated with vitiligo and further validated CDK10 by qRT-PCR in independent samples." (PMID 33679896, 2021). "To determine if genetic variant rs77651727 was shared across vitiligo, transcript of CDK10 in the blood and skin tissue, and cg05175606, we performed a colocalization analysis and detected that transcript of CDK10 in the blood and skin tissue were colocalized with cg05175606 at rs77651727." (PMID 33679896, 2021). "The SNP-association signal is significant and consistent across GWAS, eQTLGen, GTEx skin eQTL, and mQTL implying a plausible mechanism in which rs77651727 at the enhancer region alters the cg05175606 and up-regulates the expression of the CDK10 and therefore decreases the risk of vitiligo." (PMID 33679896, 2021). "rs77651727, cg05175606, and CDK10 constructed a regulatory network involving cell proliferation, differentiation, and death, which might alter the risk of vitiligo." (PMID 33679896, 2021). "Based on all these evidences, we speculate that rs77651727 is a candidate causal variant of vitiligo susceptibility, and the protective role of rs77651727 on vitiligo is mediated by altering the cg05175606 as well as up-regulating distal gene expression of CDK10." (PMID 33679896, 2021). "We finally identified cg05175606 was involved in relatively distal regulation of gene expression of CDK10 (PSMR = 3.8 × 10–14, PHEIDI > 0.01) and associated with vitiligo (PSMR = 4.67 × 10–7, PHEIDI > 0.01)." (PMID 33679896, 2021). "qPCR also confirmed that CDK10 is up-regulated in the blood of vitiligo patients relative to healthy controls." (PMID 33679896, 2021). "Differential gene expression analysis confirmed that mRNA level of CDK10 was significantly increased in the blood of vitiligo (p = 0.032)." (PMID 33679896, 2021). "To identify DNAm sites mapping to both vitiligo and transcript of CDK10, we firstly performed SMR and HEIDI analysis to test the associations of DNAm sites with vitiligo by integrating the GWAS and meQTL data." (PMID 33679896, 2021). "Further studies will be required for elucidating the regulatory network among these elements and the functional mechanisms of CDK10 in the pathogenesis of vitiligo." (PMID 33679896, 2021). "Given the direction of transcripts effect on vitiligo, CDK10 was up-regulated in both the blood and skin lesion of vitiligo (bSMR > 0)." (PMID 33679896, 2021). "Therefore, cg05175606 was mapped both CDK10 and vitiligo, and located at the promoter region according to the chromatin state annotations from the Roadmap Epigenomics Mapping Consortium (REMC) reference samples." (PMID 33679896, 2021). "Then we discovered that cg05175606 was mapped to both CDK10 and vitiligo." (PMID 33679896, 2021). "We noted that vitiligo was not colocalized with transcript of CDK10 and cg05175606." (PMID 33679896, 2021).
breast tumors (1 paper, 2012). "Patients with ER(+) breast tumors with low levels of CDK10 (Cyclin-dependent kinase 10) relapsed early under tamoxifen treatment." (PMID 23344024, 2012).
corneal diseases (1 paper, 2025). "Additionally, we examined the expression level of cyclin-dependent kinase 10 (CDK10), a cell cycle regulatory protein that was identified by our GEO dataset analysis to be associated with corneal diseases." (PMID 40155750, 2025).
endometriosis (1 paper, 2020). The growth of functional endometrial tissue in anatomic sites outside the uterine body. "Five genes (ANXA4, CDA, CDK10, DST, and HSP90AB1) from the catalogue were reported to be associated with endometriosis at two omics levels, for example ANXA4 gene at transcriptomics and ANXA4 at proteomics level." (PMID 32474803, 2020).
Fanconi anemia complementation group A (1 paper, 2018). Fanconi anemia complementation group A is a protein which in humans is encoded by the FANCA gene. "At 16q24, imputed expression levels of two genes were negatively associated with cSCC: CDK10 (cyclin dependent kinase 10) imputed in all four tested tissue types, and FANCA (Fanconi anemia complementation group A) imputed in LCLs." (PMID 30323283, 2018).
gallbladder cancer (1 paper, 2021). "Specifically, CDK10 was significantly downregulated in intrahepatic cholangiocarcinoma and gallbladder cancer, compared to normal tissue." (PMID 34277407, 2021). "Furthermore, overexpression of CDK10 increased gall bladder cancer sensitivity to gemcitabine." (PMID 34277407, 2021).
keloid (1 paper, 2012). An irregularly shaped, elevated mark on the skin caused by deposits of excessive amounts of collagen during wound healing. "In this study, first a comparative study of CDK10 mRNA and protein expression in 23 human keloid and adjacent normal skin tissue samples by quantitative real-time PCR and Western blot assay was undertaken." (PMID 22298115, 2012). "Further studies are demanded to further discuss the mechanism of CDK10 and the relationship with tamoxifen in keloid cells." (PMID 22298115, 2012). "In this paper, mRNA and protein expression of CDK10 were first investigated by a comparative study between 23 human keloid tissue samples and their adjacent normal skin." (PMID 22298115, 2012). "As such, these data confirmed the synergistic affect of CDK10 expression in combination with tamoxifen treatment on keloid apoptosis rates." (PMID 22298115, 2012). "Results showed that there is a generally down-regulated expression of CDK10 in keloid compared to normal skin samples." (PMID 22298115, 2012). "The findings indicated that CDK10 is an attractive therapeutic target because of its ability to suppress keloid fibroblast growth and enhance tamoxifen sensitivity in keloid." (PMID 22298115, 2012). "Although the mechanism of CDK10 action is unclear, CDK10 can be taken as a potential marker for sensitivity in prospective clinical trials of keloid patients treated with tamoxifen therapies." (PMID 22298115, 2012). "In this study, real-time PCR and Western blot were used to detect the level of CDK10 mRNA and protein level in 23 patients with keloid and adjacent normal skin samples." (PMID 22298115, 2012). "In the present study, a lower expression of CDK10 was found by a comparative study of mRNA and protein expression in 23 human keloid and adjacent normal skin tissue samples by quantitative real-time PCR and Western blot assay." (PMID 22298115, 2012). "Then, whether CDK10 expression was relevant to tamoxifen sensitivity in keloid was investigated by MTT, flow cytometry and Western blot assay." (PMID 22298115, 2012). "The results suggested that CDK10 may play an important role in enhancement of tamoxifen efficiency, and its expression may have a synergistic effect on keloid treatments." (PMID 22298115, 2012). "This evidence may indicate that in keloid the CDK10 may play a role by the same principle." (PMID 22298115, 2012). "CDK10 silences increases ETS2-driven transcription of c-RAF, resulting in MAPK pathway activation and loss of tumor cell reliance upon estrogen signaling, but to the best of our knowledge, there are still no literature reports on the roles of CDK10 in keloid pathogenesis." (PMID 22298115, 2012). "So far, there is no research showing the expression of CDK10 in keloid tissues." (PMID 22298115, 2012).
Urea (1 paper, 2025). "For cell cycle-related CDKs, one CDK10 and three CDKA genes were upregulated, while two CDKA genes were downregulated in the Urea group, two CDKA were downregulated in the NH4+ group, and no CDK was regulated in the NO3- group." (PMID 39772785, 2025).
tumor (20 papers, 2009 to 2025). "They found that CDK10 protein expression was decreased in GC, and loss of CDK10 expression correlated with advanced tumor stage and unfavorable OS." (PMID 34830815, 2021). "In BTC, downregulation of CDK10 gene expression and CDK10 protein was observed in cancer tissue and cell lines, and was adversely associated with tumor stage, and lymph node invasion." (PMID 34277407, 2021). "CDK10 has been implicated as both a tumor suppressor and an oncogene in gastrointestinal and hepatobiliary cancers." (PMID 34277407, 2021). "The CDK-family member Cdk10 is important for neural development and can act as a tumour suppressor, but the underlying molecular mechanisms are largely unknown." (PMID 35291876, 2022). "RNF115 triggers cell proliferation, EMT, and tumor metastasis by ubiquitinating and degrading CDK10." (PMID 38376606, 2024). "The suppressive influence of RNF115 on CDK10 expression was further corroborated in THCA tumor tissues through IHC." (PMID 38376606, 2024). "Generally, the E2F6 regulates the gene expression of proteins involved in cell proliferation and the CDK10 acts as a tumor suppressor." (PMID 37396909, 2023). "Examination of HCC tumor tissue revealed decreased expression of CDK10 mRNA and CDK10 protein compared to adjacent normal liver tissue." (PMID 34277407, 2021). "Further studies are warranted to understand the tissue-specific functions of CDK10 and the mechanisms that influence its oncogenic and tumor suppressive potential in gastrointestinal cancer." (PMID 34277407, 2021). "Additional studies have demonstrated tumor suppressive and oncogenic roles for CDK10 in other malignancies." (PMID 34277407, 2021). "Significantly, CDK10 abundance was found to be inversely correlated to tumor size and tumor stage in HCC." (PMID 34277407, 2021). "Consistently, suppression of CDK10 in patient-derived xenograft CRC tumors inhibited tumor growth and decreased expression of Bcl-2 in vivo." (PMID 34277407, 2021). "Given that CDK10 acts as a tumor suppressor in some gastrointestinal and hepatobiliary cancers, future drug development should focus on inhibiting other CDKs, while maintaining activity of CDK10." (PMID 34277407, 2021). "In contrast several lines of evidence provide insights into potential mechanism by which cdk10 act like a putative new tumor suppressor gene in multiple types of human cancers." (PMID 31413335, 2019). "High copy numbers of a region containing CDK10 have been associated with better survival of patients with oropharyngeal SCC42, and CDK10 also acts as a tumor suppressor in several other cancers, consistent with its observed negative association with cSCC." (PMID 30323283, 2018). "In some studies, CDK10 has been shown to promote cell proliferation whereas other studies have revealed a tumor suppressor function." (PMID 28178678, 2017). "In apparent contradiction with its documented positive role in cell cycle regulation, CDK10 was found to act as a tumor suppressor in a number of tumor cells." (PMID 28178678, 2017). "To support our proposals, we systematically examined the expression of CDK10 in human tumor tissue and cell lines." (PMID 22209942, 2012). "We also compared the expression of CDK10 between four different tumor cell lines (GBC-SD, HCCC-9180, SSP25 and RBE) and normal BECs." (PMID 22209942, 2012). "The molecular mechanisms by which Cdk10 suppresses tumour growth are not well understood to date." (PMID 35291876, 2022). "For example, CDK10 was found upregulated in tumor prostate specimens and seminomas." (PMID 28178678, 2017). "Finally, to account for the decreased expression of CDK10 in some patients, the methylation status of the CpG island in the CDK10 gene promoter was examined on the second tumor set." (PMID 28178678, 2017).